SHROOM4 (shroom family member 4)
Description:
Probable regulator of cytoskeletal architecture that plays an important role in development. May regulate cellular and cytoskeletal architecture by modulating the spatial distribution of myosin II (By similarity).
Synonyms: KIAA1202; SHAP; Shrm4; MRXSSDS
Tractability: No criterion of Open Targets' tractability assessment is met for any kind of drug.
Gene: Protein-coding gene on chromosome X (50,586,796 to 50,814,302, reverse strand). Ensembl gene ENSG00000158352.
Subcellular location: Cytoplasm, cytoskeleton
Subcellular location (Human Protein Atlas): Focal adhesion sites; Nucleoplasm; Vesicles
Gene Ontology:
Molecular function: protein binding; actin filament binding; myosin II binding
Biological process: brain development; cell morphogenesis; cognition; actin cytoskeleton organization; actin filament organization; regulation of postsynaptic membrane neurotransmitter receptor levels
Cellular component: actin filament; cytoplasmic side of plasma membrane; actin cytoskeleton; adherens junction; apical junction complex; apical plasma membrane; basal plasma membrane; cortical actin cytoskeleton; cytoplasm; stress fiber; cytoskeleton; GABA-ergic synapse; glutamatergic synapse; postsynapse; presynapse
Gene-disease validity (ClinGen):
ClinGen rates the evidence that SHROOM4 causes each of these diseases.
X-linked complex neurodevelopmental disorder (X-linked): Disputed. A complex neurodevelopmental disorder that is transmitted via X-linked inheritance, and is characterized by intellectual disability, autism and epilepsy.
Homologues: Orthologues: chimpanzee SHROOM4 (99% identical), macaque SHROOM4 (97% identical), pig SHROOM4 (87% identical), rabbit SHROOM4 (86% identical), dog SHROOM4 (85% identical), guinea pig SHROOM4 (80% identical), rat Shroom4 (78% identical), mouse Shroom4 (78% identical), tropical clawed frog shroom4 (38% identical), Drosophila melanogaster Shrm (13% identical), zebrafish shroom4 (4% identical). Paralogues in human: SHROOM3 (25% identical), SHROOM2 (22% identical), SHROOM1 (10% identical).
Diseases named in the same sentence as SHROOM4 in open-access papers:
SHROOM4 is named in the same sentence as 21 diseases in open-access papers, as found by Europe PMC text mining. Sharing a sentence is not in itself a finding about the gene and the disease. The quoted sentences say what the papers report.
Intellectual disability (7 papers, 2015 to 2025). "Mutations in Shroom4 have been linked to intellectual disability." (PMID 26077244, 2015). "SHROOM4 was potentially a candidate pathogenic gene of idiopathic epilepsy without intellectual disability." (PMID 35663265, 2022).
epilepsy (3 papers, 2017 to 2022). A brain disorder characterized by episodes of abnormally increased neuronal discharge resulting in transient episodes of sensory or motor neurological dysfunction, or psychic dysfunction. "Six novel hemizygous missense variants of SHROOM4 were identified in six unrelated cases with epilepsy with generalized seizures or generalized discharges on electroencephalography (EEG)." (PMID 35663265, 2022). "This study suggests that SHROOM4 is potentially a candidate causative gene of X-link epilepsy with features of generalized seizures or generalized discharges." (PMID 35663265, 2022). "In this study, we investigated the association between SHROOM4 and epilepsy." (PMID 35663265, 2022). "However, the relationship between SHROOM4 mutations and epilepsy remains uncertain." (PMID 35663265, 2022). "The SHROOM4 gene is one of the curated epilepsy genes, and its pLI score is 1.0 suggesting that it would be intolerant of protein-truncating variants." (PMID 35937050, 2022). "Two genes among them were included in curated epilepsy genes, and we could find compound heterozygous variants of GRM7, c.589C>T (p.Arg197Cys), and c.1972C>T (p.Arg658Trp), and a hemizygous splicing variant of SHROOM4 (c.269+4A>G)." (PMID 35937050, 2022). "However, the relationship between SHROOM4 gene mutations and epilepsy is not determined." (PMID 35663265, 2022). "In this study, we identified six novel hemizygous missense variants in six unrelated cases with idiopathic epilepsy but without ID, suggesting that SHROOM4 is potentially a candidate gene of epilepsy." (PMID 35663265, 2022).
Dent disease (2 papers, 2015 to 2019). Dent disease is a rare genetic renal tubular disease characterized by manifestations of proximal tubule dysfunction. "Two interstitial microdeletions Xp11.22 including the CLCN5 and SHROOM4 genes were recently reported in a male individual affected with Dent disease, short stature, psychomotor delay and minor facial anomalies." (PMID 30630535, 2019).
lung adenocarcinoma (2 papers, 2022 to 2025). A carcinoma that arises from the lung and is characterized by the presence of malignant glandular epithelial cells. "Consequently, this study aims to provide a comprehensive investigation into the expression of SHROOM4 in NSCLC and its correlation with clinical outcomes and molecular features, with particular emphasis on lung adenocarcinoma (LUAD) and lung squamous cell carcinoma (LUSC)." (PMID 41573567, 2025).
microcephaly (2 papers, 2019 to 2022). A congenital or acquired developmental disorder in which the circumference of the head is smaller than normal for the person's age and sex. "The Stocco dos Santos type of X-linked syndromic intellectual developmental disorder and Rett-like syndrome are caused by variants in the SHROOM4, with microcephaly as an occasional phenotype." (PMID 36118902, 2022).
lung carcinoma (1 paper, 2025). "We analyzed in detail the gene and phosphorylation expression patterns of SHROOM4 in NSCLC, particularly its potential functions, mutation status, immunity and distinct prognostic values of SHROOM4 in lung cancer." (PMID 41573567, 2025). "Further studies are essential to elucidate SHROOM4’s role in lung cancer progression and to validate its clinical utility." (PMID 41573567, 2025). "Our findings underscore a significant link between SHROOM4 and lung cancer, prompting us to delve deeper into its genetic underpinnings." (PMID 41573567, 2025). "Compared with adjacent non-tumor tissues, paired analysis confirmed the significant downregulation of SHROOM4 in lung cancer, specifically in LUAD and LUSC." (PMID 41573567, 2025). "Collectively, the survival probability of lung cancer patients with high-level of SHROOM4 was significantly longer than those with low-level SHROOM4, indicating high mRNA expression of SHROOM4 is a biomarker of positive prognosis in lung cancer." (PMID 41573567, 2025). "SHROOM4 expression showed significant correlations with immune infiltration scores in lung cancer." (PMID 41573567, 2025). "And mRNA expression of SHROOM4 exhibited the most greatest difference in mRNA expression in lung cancer (95% CI: -2.4887–2.3058, difference -2.2626), especially notable in patients with LUAD (95% CI: -2.0555–1.5456, difference -1.7991) and LUSC (95% CI: -2.9622–2.4744, difference -2.7234)." (PMID 41573567, 2025). "However, further functional studies are required to elucidate the precise mechanisms by which SHROOM4 influences lung cancer progression and to confirm its clinical applicability in the management of NSCLC." (PMID 41573567, 2025). "Furthermore, elevated SHROOM4 expression is associated with favorable overall survival (OS), disease-free survival (FPS), and progression-free survival (PPS) in lung cancer, exhibiting high diagnostic accuracy, especially in LUSC." (PMID 41573567, 2025). "Here, we also linked the survival possibility to the relationship between cytotoxic T lymphocytes (CTL) abundance and SHROOM4 expression and addicted that a higher abundance of CTLs may have an anti-tumor effect, particularly in the group of patients with low SHROOM4 expression in lung cancer." (PMID 41573567, 2025).
lung squamous cell carcinoma (1 paper, 2025). "And we validated the mRNA and protein expression of SHROOM4 in lung squamous cell carcinoma (LUSC) tissues and corresponding normal tissues." (PMID 41573567, 2025).
X-linked intellectual disability (1 paper, 2019). An X-linked intellectual deficiency in which not enough information is known, reported or published to indicate whether a gene causes non-syndromic or syndromic presentations. "SHROOM4, which is partially deleted in this patient, is involved in neuronal development and was shown to be associated with X-linked intellectual disability." (PMID 30630535, 2019).
tumor (2 papers, 2021 to 2025). "Pathway enrichment analysis links SHROOM4 expression to hallmark angiogenesis and Wnt/β-catenin signaling pathways, both of which are key drivers of tumor progression and microenvironment remodeling." (PMID 41573567, 2025). "The loss of SHROOM4 further promotes tumor progression and metastasis by upregulating the expression of SFTPC, thereby enhancing the Wnt/β-catenin signaling pathway." (PMID 41573567, 2025). "Subsequently, we divided the tumor tissues into a high IHC score group and a low IHC score group, then analyzed the IHC scores of SHROOM4 in these two groups." (PMID 41573567, 2025). "Low expression of SHROOM4 reduces the tumor-suppressive effect of PTPN13, leading to uncontrolled cell cycle progression in LUAD." (PMID 41573567, 2025). "Meanwhile, SHROOM4 was found to co-express with PTPN13/CACNA1C impacting the tumor microenvironment (TME) and to participate in critical signaling pathways like cell circle and WNT." (PMID 41573567, 2025). "UMAP feature plots further confirm the spatial distribution of SHROOM4, with its expression concentrated in stromal cells, reinforcing its potential role in the tumor microenvironment." (PMID 41573567, 2025). "SHROOM4 likely controls tumor progression and metastasis via the Wnt/β-catenin signaling pathway through the modulation of SFTPC." (PMID 41573567, 2025). "Furthermore, SHROOM4 appears to regulate the tumor microenvironment (TME) through mechanisms such as angiogenesis and cell cycle modulation mediated by ANGPTL7 and PTPN13 in LUAD, thereby influencing cancer progression." (PMID 41573567, 2025). "The results showed that SHROOM4 expression was positively correlated with immune infiltration scores, especially in Tcm_CD8, Tcm_CD4, and Treg cells, indicating that SHROOM4 might attract immune cells to the tumor microenvironment." (PMID 41573567, 2025). "Given the critical role of TME in mediating cancer progression and the fact that tumor-infiltrating immune cells are an integral component of TME, we sought to investigate the relationship between SHROOM4 and immune infiltration in NSCLC." (PMID 41573567, 2025). "Our findings indicate a significant downregulation of SHROOM4 at both the mRNA and protein levels in LUAD and LUSC tissues, relative to adjacent non-tumor tissues." (PMID 41573567, 2025). "In conclusion, our results indicate that low expression of SHROOM4 in LUAD and LUSC leads to the exhaustion of immune cells, impairing the body’s ability to effectively target and kill tumor cells." (PMID 41573567, 2025). "Notably, SHROOM4 is predominantly expressed in stromal cells, while SHROOM3 is more highly expressed in malignant tumor cells." (PMID 41573567, 2025). "On the other hand, the protein levels of SHROOM4 in LUSC tumor tissues were significantly lower than those in adjacent normal tissues (difference -24.45 ± 2.117, p < 0.0001)." (PMID 41573567, 2025). "Another, according to the Context++ score percentile (score > 70) in the TargetScanHuman, we selected the tumor suppressor USP49 with high Context++ score for the subsequent analysis when compared with IL17RD (score = 58), FOSB (score = 88) and SHROOM4 (score = 21)." (PMID 34075026, 2021).
cancer (1 paper, 2025). A tumor composed of atypical neoplastic, often pleomorphic cells that invade other tissues. "Using the cBioPortal for Cancer Genomics, SHROOM4 mutations were observed across various cancer types, with different mutation types including missense, frame shift, nonsense, and in-frame mutations." (PMID 41573567, 2025). "In our study using proteomics data from the CPTAC, we found that SHROOM4 expression is generally downregulated across various cancers when compared to normal tissues." (PMID 41573567, 2025). "The oncoplot displayed the mutation profiles of SHROOM4 and other frequently mutated genes in LUAD & LUSC, highlighting the mutation burden in these cancers." (PMID 41573567, 2025). "Abnormal expression of SHROOM4 was reported in some cancers." (PMID 41573567, 2025). "While SHROOM4 has been primarily studied in the context of Stocco dos Santos syndrome (OMIM #30034), its role and mechanisms in cancer biology remain underexplored." (PMID 41573567, 2025).
neurodevelopmental disorder (1 paper, 2025). A behavioral and cognitive disorder with onset during the developmental period that involves impaired or aberrant development of intellectual, motor, or social functions. "Variants in ASD-associated genes (CHD8, FOXP1, and SHANK1) and genes linked to other neurodevelopmental disorders (CDH15, GATAD2B, and SHROOM4) were also detected." (PMID 40642607, 2025).
SHROOM4 also shares sentences with these, for which no sentence is quoted: developmental delay (2 papers); Anxiety (1); CHARGE syndrome (1); cognitive disorder (1); generalized epilepsy (1); non-small cell lung carcinoma (1); Rett-like syndrome (1); Seizure (1); Stocco Dos Santos syndrome (1); X-linked mental retardation syndrome (1).